LRP1B (LDL receptor related protein 1B)
Diseases named in the same sentence as LRP1B in open-access papers (continued):
Sharing a sentence is not in itself a finding about the gene and the disease.
angiosarcoma (1 paper, 2022). A malignant tumor arising from the endothelial cells of the blood vessels.
autism (1 paper, 2013). Persistent deficits in social interaction and communication and interaction as well as a markedly restricted repertoire of activity and interest as well as repetitive patterns of behavior. "One SNP with nominal association in family-based samples is in a region previously reported in a rare deletion in a case with autism features – rs4245867 located between NXPH2 and LRP1B." (PMID 24204716, 2013).
B-cell neoplasm (1 paper, 2024). A group of heterogeneous lymphoid tumors generally expressing one or more B-cell antigens or representing malignant transformations of B-lymphocytes. "Remarkably, we found a truncated form of the low density lipoprotein receptor LRP1B transcript to be aberrantly overexpressed in about half of hairy cell leukemia variant (HCL-V) samples and, to a lesser extent, in closely related B-cell neoplasms." (PMID 38769532, 2024).
bacteremia (1 paper, 2024). "In this report, we present a complicated case of an mCRC patient with MSI-H and mutations in β2M and LRP1B proteins, complicated by concurrent bacteremia and liver fluke infection, who received first-line anti-PD1 therapy." (PMID 39193390, 2024). "In the case report, we present the clinical findings of an mCRC patient with MSI-H and mutations in Beta 2-microglubulin (β2M) and lipoprotein receptor-related protein 1B (LRP1B), who was concomitantly treated for bacteremia and liver fluke infection." (PMID 39193390, 2024).
benign neoplasms of the brain (1 paper, 2022). "Four signals associated with LRP1B (rs7599907), FRMD3 (rs10121898), MC4R (rs8087522), and ETS1 (rs76404385) identified benign neoplasms of the brain." (PMID 35887658, 2022).
bone sarcoma (1 paper, 2023). A sarcoma that arises from the bone.
breast tumors (1 paper, 2024). "C2 and C5 mainly resided in breast tumors and expressed tumor suppressor genes (EXT1 and HPSE2), which may regulate the heparan sulfate in the breast TME; C13 mainly resided in breast NAT and highly expressed LRP1B, a putative tumor suppressor that may inhibit cancer migration and invasion." (PMID 38010945, 2024).
cervical tumors (1 paper, 2012). "A homozygous loss of LRP1B in several cervical tumors was found using array-based comparative genomic hybridization analysis." (PMID 22761851, 2012).
Fanconi Anaemia (1 paper, 2022). "These include variants in genes encoding FANCE, a subunit of the Fanconi Anaemia (FA) nuclear complex; NKX2-1, a transcription factor and negative regulator of the NF-κB signalling pathway; and other recognized oncogenes JAK2, PRDM16, BMPR1A and tumor-suppressor genes KMT2C, FAT4, and LRP1B." (PMID 35954343, 2022).
gestational diabetes mellitus (1 paper, 2023). "Placental DNA methylation levels of LRP1B, which was significant only in female primary cells, and codes for a low-density lipoprotein receptor, had previously been linked with gestational diabetes mellitus and maternal glucose levels." (PMID 36695872, 2023).
glaucoma (1 paper, 2012). Increased pressure in the eyeball due to obstruction of the outflow of aqueous humor. "Of these, only the CDKN2BAS and SIX1/SIX6 regions were significantly associated with glaucoma in the meta-analysis, although several other previously identified gene regions demonstrated suggestive associations including SALL1, LRP1B and SIRPA." (PMID 22570617, 2012).
hemangioblastoma (1 paper, 2020). "We detected LRP1B frameshift, splice and missense variants of unknown significance, some of which having been previously reported in carcinomas or hemangioblastoma." (PMID 31963394, 2020).
keratoconus (1 paper, 2023). A degenerative, structural disorder of the eye, characterized by a cone-shaped protrusion of the cornea. "Four variants in LRP1B appear to be the cause of keratoconus development in four families." (PMID 37895187, 2023).
lupus (1 paper, 2018). "Further, trimethylation of histone H3 at lysine 4 (H3K4) molecules at PTPN22 (protein tyrosine phosphatase, non-receptor type 22) and LRP1B (LDL receptor related protein 1B) genes positively correlate with lupus severity and is annotated as “histone modification” (VariO:0453)." (PMID 30591019, 2018).
malignant pheochromocytoma (1 paper, 2022). "For instance, one of such subpopulation-specific markers is Lrp1b, and the mutations in Lrp1b lead to development of malignant pheochromocytoma and paraganglioma." (PMID 36237181, 2022).
monoclonal gammopathy (1 paper, 2024). A condition characterized by the abnormal presence of monoclonal immunoglobulins in the blood or urine. "Additionally, the LRP1B signature showed a strong association with proteasome inhibitor pathways, notably predicting patient responses to bortezomib and the progression from monoclonal gammopathy of unknown significance to MM." (PMID 39250742, 2024).
multiple myeloma (1 paper, 2024). "The other three cases with high LRP1B expression were found within multiple myeloma (MM), and no case was found in any of the other 20 entities." (PMID 38769532, 2024).
nasopharyngeal carcinoma (1 paper, 2020). A carcinoma arising from the nasopharyngeal epithelium. "Additionally, somatic mutations in LRP1B correlate with tumor mutation burden status in several cancers, e.g., nasopharyngeal carcinoma, and LRP1B has been proposed as a single gene surrogate to this status (mutational load, in other words,), which correlates with response to immunotherapy." (PMID 33255265, 2020).
pancreatic ductal adenocarcinoma (1 paper, 2021). An infiltrating adenocarcinoma that arises from the epithelial cells of the pancreas. "Also, concomitant mutations of KRAS and LRP1B were associated with worse disease-free survival in pancreatic ductal adenocarcinoma." (PMID 34680332, 2021).
papilloma (1 paper, 2021). A benign epithelial neoplasm that projects above the surrounding epithelial surface and consists of villous or arborescent outgrowths of fibrovascular stroma.
psoriasis (1 paper, 2022). An autoimmune condition characterized by red, well-delineated plaques with silvery scales that are usually on the extensor surfaces and scalp. "One selection signal in common type Labrador retriever cases positions across the TBC1D1 gene (body weight) and one signal of selection in working type German shepherd controls overlaps the LRP1B gene (brain), near the KYNU gene (psoriasis)." (PMID 36482174, 2022).
psychosis (1 paper, 2020). "LRP1B was identified in a GWAS where it was found to be associated with increased ventricular volumes in psychosis." (PMID 33004014, 2020).
rectal carcinoma (1 paper, 2024). A malignant epithelial neoplasm that arises from the rectum and invades through the muscularis mucosa into the submucosa. "LRP1B is considered a tumor suppressor and its somatic mutability was recently associated with improved OS of CRC patients, higher tumor mutation burden and tumor neoantigen burden connected with benefit from PD-1 blockade in MMR-proficient rectal carcinomas." (PMID 39030589, 2024).
synovial sarcoma (1 paper, 2024). "In subject 1, a synovial sarcoma, LRP1B V974I hotspot mutation, was shared across all whereas SS18_SSX2 fusion was detected only in initial biopsy." (PMID 38347552, 2024).
thyrotoxic periodic paralysis (1 paper, 2024). Thyrotoxic periodic paralysis (TPP) is a rare neurological disease characterized by recurrent episodes of paralysis and hypokalemia during a thyrotoxic state. "Furthermore, gene set enrichment analysis revealed associations of LRP1B and RYR2 with thyrotoxic periodic paralysis." (PMID 39770638, 2024).
triple-negative breast carcinoma (1 paper, 2022). An invasive breast carcinoma which is negative for expression of estrogen receptor (ER), progesterone receptor (PR), and human epidermal growth factor receptor 2 (HER2). "Frequent inactivating mutations of LRP1B have been observed in many malignant tumors, including triple-negative breast cancer, whereas its mutation could still have a functional consequence in tumorigenesis and heterogeneity." (PMID 36585729, 2022).
uveal melanoma (1 paper, 2024). A melanoma derived from melanocytes of the uveal tract. "Additionally, germline SNPs at the introns of LRP1B were recently associated with uveal melanoma." (PMID 38308491, 2024).
tumor (201 papers, 2010 to 2026). "Variants in the tumor suppressor LRP1B have recently been linked to better outcomes following ICB treatment in multiple cancers, including NSCLC." (PMID 40011914, 2025). "The tumor suppressor LRP1B, known to correlate with high tumor mutational burden and increased neoantigen load, was frequently co-mutated with KMT2C and EP300, particularly in UTUC, where both LRP1B and chromatin remodeling genes are recurrently altered." (PMID 41395625, 2025). "The expression of LRP1B was associated with different cellular phenotypes in tumor microenvironment." (PMID 40170839, 2025). "To further understand the association between LRP1B dysregulation and tumor immune microenvironment alteration, we performed a combined bulk RNA-seq and single-cell RNA-seq analysis based on 15 racially diverse, treatment-naïve CRC patient tissue samples." (PMID 40170839, 2025). "Mutations in the LRP1B gene have been documented to correlate with a high tumor mutation burden, and they have also been linked to a more favorable response to immunotherapy." (PMID 39744567, 2025). "They found that mutation of the low-density lipoprotein receptor-related protein (LRP1B) was associated with cCR (p = 0.03) and a tumor shrinkage of more than 50% (p = 0.04)." (PMID 40647527, 2025). "Comparative analyses showed that the cell subcluster distributions of CD4+ T cells, CD8+ T cells, memory B cells, stem-like epithelial cells, and tumor-associated macrophages were significantly increased in the LRP1B high-expression group." (PMID 40170839, 2025). "In our research, we discovered that LRP1B had the ability to control tumor cell susceptibility to ferroptosis induced by erastin." (PMID 39660409, 2024). "In CC with LRP1B integration, down‐regulation of LRP1B expression was associated with higher expression of total and spliced E6 expression, known to accelerate tumour growth and migration and to increase chemotherapy resistance in other tumours." (PMID 38279874, 2024). "LRP1B mutation can facilitate immune cell infiltration and immune gene expressions in the tumor microenvironment (TME)." (PMID 39193390, 2024). "The LRP1B signature effectively distinguished high-risk patients within low/intermediate-risk categories and correlated with significant changes in the tumor immune microenvironment." (PMID 39250742, 2024). "The association between LRP1B mutation and the density of tumor‐infiltrating lymphocytes (TILs) in NSCLC was investigated comprehensively." (PMID 36282125, 2023). "We used the CIBERSORT deconvolution algorithm to uncover the association between the LRP1B mutations and the 22 tumor‐infiltrating immune cells in LUAD and LUSD patients." (PMID 36282125, 2023). "LRP1B is a tumor suppressor, but LRP1B-mutated cancers have improved outcomes with ICIs, the underlying mechanism of which has not yet been clarified." (PMID 36909185, 2023). "The association between the loss of LRP1B and genetic instability (high tumor mutation burden) has been noted in several types of cancers and has been linked to a high response rate to immune checkpoint inhibitors, resulting in favorable patient outcomes." (PMID 37511044, 2023). "LRP1B, a putative tumor suppressor gene, encodes a member of the low density lipoprotein (LDL) receptor family, and is among the most frequently altered genes in human cancers, by a variety of both genetic and epigenetic mechanisms." (PMID 37079639, 2023). "BAP1 and LRP1B mutations were found in the MPM693 tumor and corresponding patient-derived cell line." (PMID 37345150, 2023). "We found that LRP1B mutation was associated with more PD-L1 positive, larger tumor size, higher CRP level, and bTMB value." (PMID 35902848, 2022).
tumor (continued). "The expression level of LRP1B is reduced in many tumors and it is among the top 10 mutated genes in the tumor." (PMID 35150083, 2022). "The LRP1B gene is considered as a putative tumor suppressor, and mutations in LRP1B are frequently observed in many cancers." (PMID 36076209, 2022). "The LRP1B gene is also a novel candidate tumor suppressor that is associated with immunotherapeutic success." (PMID 33933102, 2021). "In paired comparisons of the same patients, DICER1 and LRP1B were distinctly mutated only in tumor samples obtained after brachytherapy using rare-variant association tests (P = 0.01, 0.01, respectively)." (PMID 34545149, 2021). "Overall, LRP1B mutation was associated with tumor HPV status and was an unfavorable prognostic biomarker for CC and HNSCC." (PMID 33994859, 2021). "Apart from the known mutations, we report novel mutations in the genes AKT1, SPECC1, and LRP1B, which are linked with tumour progression and patient survival." (PMID 34796107, 2021). "LRP1B (a known tumor suppressor) deletion was associated with chemotherapy resistance in high-grade cancers." (PMID 34439350, 2021). "LRP1B is a tumor suppressor gene, encoding low-density lipoprotein (LDL) family receptor, and its mutation frequency is among the top ten in LUAD." (PMID 35069585, 2021). "To further validate the correlation of LRP1B and TSC2 in HNSCC, we analyzed them in 1478 HNSCC samples and found that LRP1B was associated with tumor HPV status in HNSCC (P = 0.044)." (PMID 33994859, 2021). "2:140988992–142889270, 1.9+ mega base pairs, 91 exons), which encodes the LDL Receptor-Related Protein 1B, a putative tumor suppressor and member of the low-density lipoprotein (LDL) receptor family that is highly expressed in the human brain." (PMID 33159041, 2020). "LRP1B encodes a large low-density lipoprotein (LDL) receptor family member with tumor suppressor activity." (PMID 31963394, 2020). "LRP1B was reported as a putative tumor suppressor gene, encoding a new member of low density lipoprotein receptor." (PMID 28522810, 2017). "Also, LRP1B mutations appeared to be associated with tumor diameter, which was more likely to be greater than 10 cm in patients with LRP1B mutations (68.75% vs. 31.25%; P = 0.01)." (PMID 38825709, 2024). "Furthermore, we observed that patients with LRP1B mutation in LUAD had significantly higher levels of tumor‐infiltrating lymphocytes (TILs) than wild‐type patients." (PMID 39660409, 2024). "Changes in the tumor environment are caused by epigenetic control of LRP1B." (PMID 38612772, 2024). "LRP1B mutations may be of clinical importance in enhancing the anti‐tumor immune response and may be a promising biomarker for predicting immunotherapy responsiveness." (PMID 36282125, 2023). "In GB in particular, LRP1B deletions are associated with poorer patient outcomes, although its functional relevance remains unknown, as for other tumor settings." (PMID 37511044, 2023). "However, the potential link between LRP1B genetic alterations and tumor mutation burden/tumor instability needs to be further addressed in other studies." (PMID 37511044, 2023).